CACNA1A (calcium voltage-gated channel subunit alpha1 A)
Diseases named in the same sentence as CACNA1A in open-access papers (continued):
Sharing a sentence is not in itself a finding about the gene and the disease.
Epileptic encephalopathy (25 papers, 2018 to 2025). A condition in which epileptiform abnormalities are believed to contribute to the progressive disturbance in cerebral function. "The best benefit of lamotrigine, which acts on the P/Q-type calcium channel, was observed in a patient with epileptic encephalopathy and the CACNA1A missense variant p.Ser1373Leu, but functional data on the variant were not reported." (PMID 40703772, 2025). "CACNA1A loss-of-function and missense variants have also been demonstrated to cause some epileptic encephalopathies, a group of severe childhood epilepsy disorders, including infantile spasms and Lennox-Gastaut Syndrome." (PMID 38491427, 2024). "Since then, cumulative research highlighted how de novo mutations in channel genes are a recurrent cause of epileptic encephalopathies and recently revealed a role also for CACNA1A variants." (PMID 33737904, 2021). "Latest clinical studies in early onset epileptic encephalopathies suggest that the mechanisms subserving epileptogenesis in the setting of pathogenic CACNA1A variants is likely more complex than anticipated." (PMID 33737904, 2021). "A phenotype compatible with epileptic encephalopathy has first been described in association with deletions and truncating mutations in CACNA1A." (PMID 33737904, 2021). "The high-voltage-activated (HVA) Cav2.1 (P/Q-type) channel, encoded by CACNA1A, has been associated with early onset epileptic encephalopathy." (PMID 32545604, 2020). "CACNA1A polymorphisms are associated with Chinese ASD, and CACNA1A mutations with epileptic encephalopathy." (PMID 31893021, 2019). "As published by the Epi4K consortium in 2016, among 531 individuals with a variety of unresolved epileptic encephalopathy, targeted sequencing identified six infants with CACNA1A pathogenic variants (including an affected sibling), which were de novo in 3/5 families." (PMID 39416668, 2024). "Here, we report a rapidly progressive and fatal course of early-onset CACNA1A associated developmental and epileptic encephalopathy in three siblings, of which two were identified to harbor compound heterozygous frameshift variants in CACNA1A and one is considered to have the same genotype." (PMID 39416668, 2024). "Furthermore, bi-allelic pathogenic variants in the CACNA1A gene have been reported in several infants with epileptic encephalopathy of early-onset and refractory course, severe muscular hypotonia and progressive cerebral, cerebellar, and optic nerve atrophy." (PMID 39416668, 2024). "Furthermore, current evidence from the field of epileptic encephalopathies supports the application of diagnostic panels covering also CACNA1A in this setting." (PMID 33737904, 2021). "In addition to seizures, patients with CACNA1A mutations and epileptic encephalopathies showed a variety of cognitive manifestations including psychomotor delay, mild to profound intellectual disability, attention deficit-hyperactive disorder (ADHD), and/or autism spectrum disorders (ASD)." (PMID 38491427, 2024). "In the largest reported series of CACNA1A-related epileptic encephalopathy, four out of six cases were upon treatment with acetazolamide or topiramate but information about the treatment response was not provided." (PMID 33737904, 2021). "Our findings suggest that the downregulation of CACNA1A in this meta-analysis may be contributing to the epileptic encephalopathy of RTT." (PMID 36232428, 2022). "In addition, mutations of calcium channels have been found in ASD, for example, CACNA1A rs7249246/rs12609735 were associated with Chinese Han ASD, and CACNA1A mutations in Epileptic Encephalopathy, gain of function of CACNA1C in Timothy syndrome with ASD and recurring CNVs of CACNA2D3." (PMID 33338084, 2020).
Dystonia (22 papers, 2008 to 2026). An abnormally increased muscular tone that causes fixed abnormal postures. "Recent reports have shown that dystonia can also be primary and/or generalized in cases with CACNA1A variants." (PMID 40533913, 2025). "We did not screen other variants for cosegregation given previously established associations between CACNA1A and dystonia." (PMID 29770609, 2018). "A notable percentage of patients with dystonia due to mutations in CACNA1A show significant improvement with acetazolamide." (PMID 29770609, 2018). "For instance, in Cacna1a mutant mice [tottering;], loss of the Cav2.1 voltage dependent calcium channel not only causes ataxic episodes, but severe dystonia can also be induced in the same mice." (PMID 24294192, 2013). "This confirms that variants in CACNA1A are also linked to isolated dystonia." (PMID 40533913, 2025). "Additionally, three homogeneous, loss-of-function CACNA1A mouse models, tottering, rocker, and tottering-4j, exhibit stress-induced attacks of dystonia, which is thought to be due to cerebellar dysfunction." (PMID 34395002, 2021). "Thus, our patient's dystonia may be due in part to cerebellar dysfunction related to her CACNA1A mutation." (PMID 34395002, 2021). "This case describes an infant with prenatal contractures of both hands, raised nuchal translucency and polyhydramnios, who developed motor delay, hypotonia, dystonia, and a saccadic eye disorder after birth, consistent with a CACNA1A‐related disorder." (PMID 40445116, 2025). "Our analysis also uncovered pathogenic or likely pathogenic variants in uncommonly dystonia-associated genes (PCCB, CACNA1A, ALDH5A1, PRKN) in four families where dystonia has been rarely observed in the spectrum of the clinical characteristics so far." (PMID 38458754, 2024). "Pathogenic or likely pathogenic variants were found in four families in genes that are not commonly associated with dystonia (PCCB, CACNA1A, ALDH5A1 and PRKN)." (PMID 38458754, 2024). "Importantly, the phenotypes associated with mutations in the DYT genes enriched in the putamen ‘cyan’ module belonged to different clinical subtypes of dystonia, namely isolated dystonia (ANO3 and HPCA), combined dystonia (KCTD17 and ADCY5), and paroxysmal dystonia (KCNA1, CACNA1A, PRRT2 and SCN8A)." (PMID 32889528, 2020). "Initial genetic analysis showed that both single-gene and panel (dystonia) sequencing were not conclusive for the following genes: ATP1A3, PRKRA, CACNA1a, DYTPRI, DYT1, and DAT1." (PMID 41153421, 2025).
Cognitive impairment (20 papers, 2015 to 2026). Abnormal cognition is characterized by deficits in thinking, reasoning, or remembering. "Indicating intrafamilial heterogeneity, the mild cognitive impairment and childhood-onset generalized epilepsy in child II-3 was associated with a CACNA1A haploinsufficiency inherited from the EA2 affected mother." (PMID 39416668, 2024). "Our analyses support that PTVs and missense variants in KDM5B, GIGYF1 and CACNA1A underlie a continuum of conditions with various degrees of cognitive impairment." (PMID 37231097, 2023). "Further electrophysiological characterization of different hippocampal regions of wild-type and Cacna1a mutant mice using the MED system would provide new insights into cognitive impairments in CACNA1A-associated disorders." (PMID 35548926, 2022). "Consistently, human studies have shown that loss of function mutations in CACNA1A lead to absence epilepsy, a generalized epilepsy frequently associated with cognitive impairments." (PMID 35548926, 2022). "CACNA1A loss-of-function mutations are associated with cognitive impairment including intellectual disability, ADHD and ASD." (PMID 31652960, 2019). "Thus, cognitive impairments in CACNA1A-associated human disorders can be generalized as hippocampus-related functional deficits." (PMID 35548926, 2022). "It indicated that the cognitive impairment caused by CACNA1A mutations was usually persistent." (PMID 33425808, 2020). "Individuals with CACNA1A mutations may display intellectual impairment (ID)." (PMID 40111503, 2025). "Thus, hippocampus-related deficits may be an important underlying hallmark of cognitive impairments accompanied with CACNA1A-associated disorders." (PMID 35548926, 2022). "However, it is unclear whether the cognitive deficits are consequences secondary to the neurological symptoms elicited by CACNA1A mutations." (PMID 35548926, 2022). "Formal neuropsychological testing revealed cognitive deficits in the majority of CACNA1A patients (19 out of 22 versus 5 out of 14 in the GAA-FGF14 group; p < 0.01 at Fisher’s exact test)." (PMID 41240219, 2025). "According to the GSEA phenotype analysis, APOE, BDNF, CACNA1A, COMT and UCHL1 were identified as the main genes associated with cognitive impairment (FDR q-value < 0.05)." (PMID 41301762, 2025). "Moreover, specific ablation of Cacna1a in mouse forebrain results in multiple cognitive impairments, and Cacna1a knock-out mice show deficits in spatial learning and reduced recognition memory." (PMID 26566276, 2015). "In conclusion, our results suggest that among the broad spectrum of CACNA1A-related phenotypes, non-progressive congenital ataxia is associated with cognitive impairment and dysmorphic features, constituting a recognizable syndromic neurodevelopmental disorder." (PMID 34068417, 2021).
Nystagmus (20 papers, 2015 to 2025). Rhythmic, involuntary oscillations of one or both eyes related to abnormality in fixation, conjugate gaze, or vestibular mechanisms. "Paroxysmal tonic up-gaze, nystagmus, and other eye movement disorders are all features of CACNA1A and present in up to 90% interictally." (PMID 34177764, 2021). "In addition, it is possible that the CACNA1A gene variants might induce BTU, an uncommon illness characterized by frequent periods of upward gazing accompanied with abnormal eye movements like nystagmus." (PMID 40111503, 2025). "CACNA1A-EA is characterized by onset, from early childhood to early adulthood, of less frequent attacks than in PxMD-KCNA1 (weekly or only a few episodes per year) with nystagmus, vertigo, nausea, vomiting and dysarthria, which last for hours." (PMID 34177764, 2021).
Intellectual disability (17 papers, 2014 to 2025). "In the past decade, the increasing availability of next generation sequencing (NGS) techniques added de novo missense CACNA1A mutations to the genetic background of intellectual disability." (PMID 33737904, 2021). "The pathophysiological basis of intellectual disability due to pathogenic CACNA1A variants is largely unexplored." (PMID 33737904, 2021). "We found that about half of the HM patients with the CACAN1A gene mutation had mental retardation, which may be related to the calcium channel impairment caused by the CACNA1A gene mutation." (PMID 37576133, 2023). "Overall, CACNA1A and ATP1A2 mutations have functional consequences, including impairments in the cognitive ability of patients and, in some cases, intellectual disability following multiple attacks." (PMID 38674378, 2024). "CACNA1A is associated with hemiplegic migraine syndromes, although it has also been described in patients with ASD, intellectual disability, and even ADHD." (PMID 38003033, 2023).
developmental and epileptic encephalopathy (15 papers, 2020 to 2026). An epilepsy associated with developmental impairment that may be due to either the underlying etiology or the superimposed epileptic activity, or both. "This is in line with previous observations of generalized absence epilepsy, refractory focal epilepsy or developmental and epileptic encephalopathy in patients with heterozygous CACNA1A loss-of-function pathogenic variants." (PMID 39416668, 2024). "Recently, Jiang and colleagues, have demonstrated that both gain- and loss-of-function Cacna1a mutations are associated with developmental epileptic encephalopathies." (PMID 32168507, 2020). "Additionally, CACNA1A variants have been associated with early-infantile developmental and epileptic encephalopathy and migratory focal epilepsy." (PMID 40111503, 2025). "Emerging evidence suggests that a similar dominant-negative effect on human CaV2.1 proteostasis may also apply to loss-of-function CACNA1A mutations associated with developmental epileptic encephalopathy." (PMID 39609819, 2024).
Parkinsonism (15 papers, 2015 to 2025). Characteristic neurologic anomaly resulting from degeneration of dopamine-generating cells in the substantia nigra, a region of the midbrain, characterized clinically by shaking, rigidity, slowness of movement and difficulty with walking and gait. "Mutations in ATXN3, PRNP, and CACNA1A have been implicated in PD and parkinsonism through diverse mechanisms and clinical presentations in isolated cases." (PMID 41009775, 2025).
Friedreich ataxia (13 papers, 2010 to 2026). An inherited condition that affects the nervous system and causes movement problems. "In European natives, pathogenic mutations should be searched in genes producing SCA1 (ATXN1), SCA2 (ATXN2), SCA3 (ATXN3), SCA6 (CACNA1A), SCA7 (ATXN7), SCA 12 (PPP2R2B), fragile X tremor ataxia syndrome (FMR1), SCA17 (TBP), CANVAS syndrome (RFC1), and Friedreich ataxia (FXN) [53﻿]." (PMID 35986227, 2023).
progressive ataxia (13 papers, 2014 to 2025). "While CACNA1A usually considers a young-onset disease, some reports have shown that pathogenic variants in this gene lead to late-onset diseases, such as episodic ataxia 2 (EA2) and progressive cerebellar ataxia (PCA)." (PMID 34727962, 2021).
Stroke (13 papers, 2011 to 2025). Sudden impairment of blood flow to a part of the brain due to occlusion or rupture of an artery to the brain. "Some individuals with CACNA1A pathogenic variants may exhibit severe symptoms, including fatal refractory brain edema, stroke-like symptoms, recurrent loss of consciousness, coma, and visual impairment." (PMID 41456028, 2025). "Thus, based on her extensive nondiagnostic workup and a previously reported individual with FHM1 and stroke related to CACNA1A variant, we propose that the de novo variant in this gene in our patient is most likely the cause of her recurrent strokes." (PMID 32692472, 2020). "While we postulate a gain‐of‐function mechanism for this Cav2.1 voltage‐gated Ca2+ channel in causing stroke in our patient, further studies are needed to understand the basis of stroke related to the p.Leu1692Gln variant and determine the specific impact of this variant on CACNA1A function." (PMID 32692472, 2020). "Another rare condition which may cause stroke in children is a rare syndrome characterized by diffuse cerebral edema and coma as a result of a mutation of the CACNA1A gene, coding for a structural protein for the calcium channel not present in the case we described." (PMID 21210991, 2011). "Our findings expand the phenotypic heterogeneity related to Cav2.1 (P/Q‐type) calcium channel dysfunction and suggest consideration of CACNA1A disorder in evaluation of pediatric strokes." (PMID 32692472, 2020). "Hence in the molecular examination for early age at onset of stroke (childhood stroke), CACNA1A should be considered." (PMID 34727962, 2021). "CACNA1A disorder should be considered part of the evaluation for pediatric strokes, particularly when the brain lesions do not align with typical vascular territories." (PMID 40111503, 2025). "Our findings expand the phenotypic heterogeneity related to Cav2.1 (P/Q‐type) calcium channel dysfunction and suggest consideration of CACNA1A disorder in evaluation of pediatric strokes, especially if the brain lesions do not conform to vascular territories." (PMID 32692472, 2020).
autism (12 papers, 2015 to 2025). Persistent deficits in social interaction and communication and interaction as well as a markedly restricted repertoire of activity and interest as well as repetitive patterns of behavior. "Further mutation screening and researches on CACNA1A function are essential to understand the underlying mechanisms of this gene on autism." (PMID 26566276, 2015). "Our results showed association between rs12609735 and rs7249246 in CACNA1A with autism in a total of 553 trios though statistical significance was not reached after Bonferroni correction." (PMID 26566276, 2015). "In the present study, we performed a family-based association study to investigate the association between CACNA1A and autism in Chinese Han population." (PMID 26566276, 2015). "Association results between 3 SNPs in CACNA1A and autism in 553 trios by FBAT under a recessive model." (PMID 26566276, 2015). "We performed a family-based association study to assess the association between CACNA1A and autism in Chinese Han population." (PMID 26566276, 2015). "Here we reported the association between CACNA1A and autism in Chinese Han population for the first time." (PMID 26566276, 2015). "Association results between 3 SNPs in CACNA1A and autism in 553 trios by FBAT under a dominant model." (PMID 26566276, 2015). "The human homolog of unc-2, CACNA1A, has also been associated with autism." (PMID 31805042, 2019). "To explore the association of CACNA1A with autism, we performed a family-based association study." (PMID 26566276, 2015). "Other important genes suggested as being related to autism, such as CACNA1A and SLC8A1, also appeared, although targeted by a smaller number of miRNAs." (PMID 40282383, 2025). "Detailed examination of epileptic patients with CACNA1A mutations has shown that a handful of them have been showing psychiatric problems including atypical social interactions, ADHD, and autism." (PMID 34727962, 2021). "CACNA1A is located on chromosome 19p13, and a previous study identified the region of suggestive linkage with autism on 19p13." (PMID 26566276, 2015). "Interestingly, many of the up-regulated genes are involved in mental conditions and higher cognitive functions, including the schizophrenia- and autism-associated gene SYN2 and cognition- and intelligence-associated genes FMN2, CTNND2, and CACNA1A 67–71." (PMID 36788214, 2023). "In summary, we detected an association of rs7249246 and rs12609735 in CACNA1A with autism though this would not survive after Bonferroni correction." (PMID 26566276, 2015). "However, the genetic relationship between autism and CACNA1A in Chinese Han population remains unclear." (PMID 26566276, 2015). "Our study indicated that CACNA1A might play a role in the pathogenetic mechanism of autism." (PMID 26566276, 2015). "Our findings suggest that CACNA1A might play a role in the etiology of autism." (PMID 26566276, 2015). "Therefore, we hypothesized that CACNA1A might be involved in the etiology of autism." (PMID 26566276, 2015).
autism spectrum disorder (12 papers, 2016 to 2026). A spectrum of developmental disorders that includes autism, and Asperger syndrome. "This case describes an adolescent with a CACNA1A pathogenic variant and autism spectrum disorder who develops catatonia and was safely and successfully treated with bilateral electroconvulsive therapy (ECT)." (PMID 42038079, 2026). "In a family study involving 79 individuals with autism spectrum disorder (ASD), including 77 trios and 2 quartets, CACNA1A has also been demonstrated to exhibit ASD-causing properties." (PMID 40111503, 2025). "Besides, CACNA2D1 is related to autism spectrum disorder while CACNA1A, CACNA1C and CACNA2D1 are candidate genes for attention deficit hyperactive disorder." (PMID 33985586, 2021). "While CACNA1A variants alone may not directly cause autistic spectrum disorders (ASD), they have been reported individuals with ASD alongside other genetic and environmental factors." (PMID 40111503, 2025).
Machado-Joseph disease (12 papers, 2014 to 2025). "The most frequent SCA worldwide are those caused by CAG repeat expansions, as SCA1 (in ATXN1), DRPLA (ATN1), SCA2 (ATXN2), Machado-Joseph disease (MJD)/ SCA3 (ATXN3), SCA6 (CACNA1A), SCA7 (ATXN7), and SCA17 (TBP), usually designated polyglutamine (polyQ) ataxias." (PMID 39048885, 2024).